RNU12-2P (RNA, U12 small nuclear 2, pseudogene)
Synonyms: U12; RNU12; RNU12P
Gene: Small nuclear RNA gene on chromosome X (47,132,671 to 47,132,826, forward strand). Ensembl gene ENSG00000201659.
Homologues: Orthologues: chimpanzee U12 (99% identical), macaque U12 (92% identical), guinea pig U12 (83% identical), pig U12 (79% identical), mouse Gm56207 (63% identical), mouse Gm55022 (60% identical). Paralogues in human: RNU12 (89% identical).
Diseases named in the same sentence as RNU12-2P in open-access papers:
RNU12-2P is named in the same sentence as 4 diseases in open-access papers, as found by Europe PMC text mining. Sharing a sentence is not in itself a finding about the gene and the disease.
RNU12-2P shares sentences with these, for which no sentence is quoted: cancer (1 paper); myositis (1); pulmonary arterial hypertension (1); spinal muscular atrophy (1).